MIR331 (microRNA 331)
Synonyms: hsa-mir-331; MIRN331; mir-331
Gene: MicroRNA gene on chromosome 12 (95,308,420 to 95,308,513, forward strand). Ensembl gene ENSG00000199172.
Gene Ontology:
Biological process: miRNA-mediated post-transcriptional gene silencing
Cellular component: RISC complex
Homologues: Orthologues: chimpanzee ptr-mir-331 (100% identical), macaque MIR331 (99% identical), guinea pig MIR331 (97% identical), mouse Mir331 (97% identical), rabbit MIR331 (96% identical), pig ssc-mir-331 (85% identical).
Diseases named in the same sentence as MIR331 in open-access papers:
MIR331 is named in the same sentence as 1 disease in open-access papers, as found by Europe PMC text mining. Sharing a sentence is not in itself a finding about the gene and the disease.
MIR331 shares sentences with these, for which no sentence is quoted: breast cancer (1 paper).